SV2A (synaptic vesicle glycoprotein 2A)
Diseases named in the same sentence as SV2A in open-access papers (continued):
Sharing a sentence is not in itself a finding about the gene and the disease.
epilepsy (continued). "The study of how the expression of SV2A varies temporally and regionally in epilepsy and other pathological contexts will improve our understanding of the pathological mechanisms, potentially pointing out new roles of SV2A, and helping in the evaluation of the SV2A imaging outcomes." (PMID 35573314, 2022). "Moreover, in the tumor and peritumoral tissues of glioma of patients with epilepsy, SV2A expression levels correlated with the clinical efficacy of LEV." (PMID 35455472, 2022). "Taken together, these results indicate that any change in SV2A expression may participate in the pathogenesis and treatment of epilepsy." (PMID 33922424, 2021). "Epilepsy is characterized by an imbalance between excitation and inhibition, hence SV2A levels in particular terminals could also influence the LEV response." (PMID 33922424, 2021). "Changes in SV2A protein expression induced during epilepsy could be a critical factor in the response to LEV treatment, since SV2A is its molecular target." (PMID 33922424, 2021). "Because epilepsy is characterized by an imbalance of excitatory to inhibitory systems and since SV2A is the main molecular target of LEV, whether GABAergic or glutamatergic terminals co-express SV2A could be decisive for LEV resistance." (PMID 33922424, 2021). "In some epileptic patients and “long-term” animal models of epilepsy, a significant reduction of SV2A is observed, supporting the idea that SV2A could endorse a role in epilepsy progression." (PMID 28588450, 2017). "Because SV2A KO mice display spontaneous and violent seizures, and as the anti-epileptic drug Levetiracetam (LEV—also known as Keppra©) targets SV2A, many studies have addressed the possible role(s) of SV2A in various pathological conditions, particularly in epilepsy pathophysiology." (PMID 28588450, 2017). "SV2A is the target of an anticonvulsant drug named Levetiracetam (Keppra®), and its expression has been reported to be reduced during epileptogenesis in rats, confirming the role this protein plays in epilepsy." (PMID 27861538, 2016). "With the aims of bypassing early lethality and analyzing SV2A’s functions in epilepsy, we thus established a conditional mouse line carrying SV2A deletion in the hippocampus, starting after P14 or, in other words, after the earliest and main postnatal stages of neurodevelopment." (PMID 27861538, 2016). "Moreover, SV2A protein expression is significantly reduced in brain tissue obtained from epileptic patients and in rats during epileptogenesis, suggesting that decreased SV2A contributes to the progression of epilepsy." (PMID 25914622, 2015). "Knowing the in vivo expression pattern of SV2A in epilepsy patients may be essential for evaluating increased epileptogenicity and thus disease progression." (PMID 25914622, 2015). "The SV2A protein has been associated to the physiopathology of epilepsy; newborn mice lacking SV2A experience severe seizures and die within 3 weeks, suggesting multiple neural alterations." (PMID 25914622, 2015). "Furthermore, brivaracetam, a novel antiepileptic drug (AED) with higher SV2A affinity than levetiracetam, shows higher potency in several preclinical models of epilepsy and is currently in clinical development." (PMID 23937191, 2013). "SV2A regulates the size of the readily releasable pool of vesicles in the majority of GABAergic neurons, and it has been suggested that reductions in its expression could potentially contribute to the etiology of epilepsy." (PMID 38776036, 2024). "They found that the SV2A immunoreactivity was decreased in all specimens from patients with confirmed hippocampal sclerosis, whereas the SV2A protein expression in the hippocampus of rats in the chronic epileptic phase was also reduced, but only in those animals with a progressive form of epilepsy." (PMID 38776036, 2024). "Thus, the use of this radiotracer opens the door to new research which could help us to finally understand the role of the SV2A protein in epilepsy." (PMID 32206990, 2020).
epilepsy (continued). "The aim of present study was therefore to verify the hypothesis that chronic LEV treatment induces changes in the expression of SV proteins other than SV2A, in line with the emerging notion that presynaptic proteins are potential therapeutic targets for epilepsy and other neurological diseases." (PMID 29311825, 2017). "Besides epilepsy, SV2A could also be involved in the pathophysiology of other neurological diseases." (PMID 28588450, 2017). "Further studies are needed to elucidate the effect of variations in the expression of SV2A on the neuronal excitability and efficacy of LEV in the treatment of epilepsy." (PMID 37845841, 2023). "In the current study, we report the generation and characterization of a novel sv2a knockout zebrafish model using CRISPR/Cas9 and the application of connectivity mapping in finding novel drug candidates against epilepsy." (PMID 35686059, 2022). "Unlike LEV, padsevonil displayed a high affinity among the different isoforms of the SV2 protein (SV2A, SV2B and SV2C) and showed a greater effect in blocking seizures in various epilepsy animal models than LEV and BRIV." (PMID 35455472, 2022). "Due to post-brain-insult epilepsy being accompanied with inflammation by brain damages, LEV has dual effects for suppressing such types of seizures; binding to SV2A to suppress exocytosis and acting on microglia to attenuate inflammation." (PMID 34681621, 2021). "SV2A is the target site of levetiracetam (LEV) and related compounds, which are approved for use in patients with multiple types of seizures and epilepsies." (PMID 33569037, 2020). "Herein, no significant changes in total SV2A expression were observed during the initial stage of epilepsy-induced by pilocarpine." (PMID 33922424, 2021). "Importantly, SV2A is the binding site of the levetiracetam (LEV), a compound largely used in human therapy for epilepsy treatment." (PMID 31560168, 2019). "The possibility thus exists that GriK4:SV2A-cKO does not affect the neuronal population responsible for epilepsy, as the GABAergic system is preserved." (PMID 27861538, 2016). "However, as previously stated, the physiopathological role of SV2A in epilepsy has not yet been clearly defined." (PMID 27861538, 2016). "The epilepsy drug levetiracetam binds to SV2A selectively and has been the basis for development of multiple radiotracers, the first of which, [11C]UCB-J, was shown to correlate with ex vivo measures of SV2A in the non-human primate." (PMID 40533661, 2025). "The slow disappearance of the SV2A protein in the CA3 and DG regions from P14 to P56 could, in this context, not lead to epilepsy onset, as this disappearance developed too late or too slowly." (PMID 27861538, 2016). "However, even without concomitant SV2A drug intake, the efficacy of PSL was modest, and 75% responder rates were not better than those observed in pivotal trials with other ASMs in populations of comparable epilepsy severity." (PMID 36176044, 2022).
Alzheimer disease (24 papers, 2019 to 2026). A progressive, neurodegenerative disease characterized by loss of function and death of nerve cells in several areas of the brain leading to loss of cognitive function such as memory and language. "Synaptic vesicle glycoprotein 2A (SV2A), a transmembrane protein widely localized to synaptic vesicles, serves as a key indicator of synaptic loss in Alzheimer's disease (AD)." (PMID 41521688, 2026). "For example, in Alzheimer’s disease, which is characterised by synapse loss during the early stages, it would be informative to determine whether and how SV2A-positive synapse types and subtypes are affected at the different stages of disease progression." (PMID 41229902, 2025). "Positron emission tomography (PET) imaging with ligands for synaptic vesicle glycoprotein 2A (SV2A) has emerged as a promising methodology for measuring synaptic density in Alzheimer's disease (AD)." (PMID 40491249, 2025). "The SV2 family of membrane glycoproteins consists of three members, SV2A, SV2B, and SV2C, and all of them have been linked to multiple neurological disorders, e.g. epilepsy, Parkinson's disease, Alzheimer's disease, and cognitive disorders." (PMID 37682518, 2024). "Intriguingly, the clinical feasibility of detecting SV2A decline has been reported in other neurodegenerative disorders, including Alzheimer disease and Parkinson disease." (PMID 34531262, 2022). "SV2A PET imaging studies have consistently reported lower synaptic density in Alzheimer’s disease." (PMID 40163154, 2025). "In this study, we sought to investigate synaptic vesicle glycoprotein 2A (SV2A) PET with [18F]UCB-H as an alternative preclinical biomarker for neurodegenerative processes in two mouse models representing the pathological hallmarks of Alzheimer’s disease (AD)." (PMID 37541098, 2023). "This hypothesis is suggested by the observed amelioration of mitochondrial dysfunctions typical of patients with Alzheimer’s disease upon administration of levetiracetam, the drug known to interact specifically with SV2A." (PMID 35573314, 2022). "More and more studies indicate that SV2A may be a key molecule in the development of Alzheimer’s disease." (PMID 34795573, 2021). "In Alzheimer’s disease patients, PET imaging with different SV2A tracers revealed a decreased binding in several cortical areas, thalamus and hippocampus." (PMID 35573314, 2022). "Synaptic vesicle glycoprotein 2A, the newly identified APP‐binding protein, reduces amyloid‐β plaque deposition in Alzheimer's disease by suppressing the amyloidogenic pathway through inhibition of BACE1‐APP interaction and alteration of APP endosomal‐lysosomal localization." (PMID 41521688, 2026). "There are now over 100 clinical studies using SV2A PET radiotracers in a wide range of disorders, including neurodegeneration (e.g. Alzheimer’s disease, frontotemporal dementia, supranuclear palsy), psychiatric disorders (e.g. schizophrenia), epilepsy and stroke." (PMID 41229902, 2025).
schizophrenia (22 papers, 2017 to 2026). A major psychotic disorder characterized by abnormalities in the perception or expression of reality. "Variations in genes that encode synaptic proteins, including genes for the synaptic vesicle glycoprotein 2 A (SV2A), an established marker of synaptic density, have been implicated in the pathophysiology of schizophrenia." (PMID 38898401, 2024). "Association between schizophrenia and a common genetic variant in the SV2A gene region (1q21.2) has also been reported." (PMID 38898401, 2024). "Our proteomic examination of 22q11.2del neurons afforded an orthogonal examination of synaptic components in these cells and independently identified significant presynaptic alterations, including alterations in the schizophrenia-associated gene SV2A, a key mediator of pre-synaptic function." (PMID 35760976, 2022). "Notably, Pclo and Sv2a have growing evidence of genetic association with schizophrenia." (PMID 41022686, 2025). "In previous work testing the relationship between SV2A and glutamate levels, there were significantly more smokers in the schizophrenia than in the healthy volunteer group." (PMID 40025026, 2025). "This is a cross-sectional study, so we are unable to determine the mechanistic links between glutamate, SV2A and schizophrenia." (PMID 40025026, 2025). "Future studies with larger sample sizes are needed to test for differences between healthy volunteer and schizophrenia groups in SV2A-glutamate correlation strength." (PMID 40025026, 2025). "This approach adjusts for nonspecific binding, providing a signal more specific to SV2A, and more sensitive to schizophrenia-related differences in SV2A levels, than VT." (PMID 40025026, 2025). "Further studies are also required to investigate the effects of stress on SV2A levels, and to relate this to schizophrenia pathophysiology." (PMID 36056106, 2023). "The SV2A PET imaging in schizophrenia thus extends post-mortem findings of lower protein and mRNA levels of synaptophysin and other presynaptic markers in samples from patients in these regions." (PMID 36056106, 2023). "The fact that lower [11 C]UCB-J levels have been reported in two independent cohorts of patients provides some confidence that there are lower SV2A levels in schizophrenia." (PMID 36056106, 2023). "Glutamatergic dysfunction is an important factor in schizophrenia onset, and SV2A density and glutamate levels in anterior cingulate cortex and hippocampus have been measured in patients with schizophrenia compared to healthy volunteers with [11C]UCB-J PET." (PMID 35573314, 2022). "For instance, neurexin 3 has been linked to autism, whereas SV2A and VAMP are associated with schizophrenia." (PMID 34827371, 2021). "In a previous study from our laboratory, we found lower SV2A levels in patients relative to controls in the ACC and hippocampus, consistent with postmortem evidence for synaptic loss in these regions in schizophrenia." (PMID 34282130, 2021). "Another possibility is that a greater proportion of the glutamate signal is extra-synaptic, and thus unrelated to SV2A, in schizophrenia." (PMID 34282130, 2021). "Here, using [11C]UCB-J PET, the authors show for the first time in vivo that levels of the synaptic marker protein SV2A are reduced in schizophrenia and unaffected by antipsychotic treatment in a rat model." (PMID 31937764, 2020). "This evidence indicates that [11C]UCB-J is a specific marker of SV2A levels, and thus that SV2A levels are reduced in schizophrenia." (PMID 31937764, 2020). "Notwithstanding this, our DVR results indicate that the lower [11C]UCB-J VT values in schizophrenia likely reflect lower specific binding to SV2A." (PMID 31937764, 2020). "Schizophrenia (SCZ) is another disorder that has been recently suspected to involve SV2A in its pathophysiology pathway." (PMID 28588450, 2017).
schizophrenia (continued). "Therefore, we conducted a multimodal [11C]UCB-J PET and 1H-MRS imaging study to test the relationship between the synaptic terminal marker SV2A and glutamate levels in unmedicated patients with schizophrenia within the first episodes of psychosis." (PMID 40025026, 2025). "In the meantime, further post-mortem studies to investigate the levels of synaptic vesicle proteins, the number of SV2A molecules per vesicle and the number of vesicles per terminal in schizophrenia, would be useful to aid interpretation of the in vivo findings." (PMID 36056106, 2023). "Finally, two recent studies using [11 C]UCB-J PET find evidence for lower levels of the synaptic terminal protein SV2A, in frontal and temporal cortices of patients with schizophrenia." (PMID 36056106, 2023). "The recent development of a new radioligand targeting the synaptic vesicle glycoprotein 2A (SV2A) demonstrated in vivo lower synaptic density at the PFC level in individuals with schizophrenia, corroborating the synaptic hypothesis of thedisease first proposed by Feinberg in 1982." (PMID 41009515, 2025). "The concept of schizophrenia as a dendritic spine pathology is regaining attention due to recent PET studies targeting the synaptic vesicle glycoprotein 2A (SV2A), a marker of synaptic density, and a revamped interest in the synaptic hypothesis of schizophrenia is occurring." (PMID 41009515, 2025). "This includes lower levels of synaptophysin and other synaptic vesicle proteins, lower transcript levels of SV2A, lower cortical dendritic spine density and other post-synaptic elements, and lower spine plasticity, in the context of unaltered neuronal numbers in schizophrenia." (PMID 37041418, 2023). "Therefore, we tested the hypothesis that SV2A and NAA levels would be directly associated in schizophrenia." (PMID 34282130, 2021). "Thus, the lower [11C]UCB-J uptake we observe in schizophrenia could be due either to a reduction in SV2A levels specifically, or a reduction in nerve terminal number manifest as decreased levels of SV2A and other synaptic protein levels." (PMID 31937764, 2020). "SV2A PET imaging, using [11C]UCB-J, in schizophrenia has shown that synaptic density is lower in chronic schizophrenia (replicated by two independent research groups) and may be present in early stages of the disorder." (PMID 40163154, 2025). "Genotyping of this schizophrenia patient population was not carried out prior to imaging and our results suggest that a more specific study examining SV2A levels in 22q11.2del carriers of varying diagnoses would be warranted." (PMID 35760976, 2022). "In addition, the novel PET tracer binds to synaptic vesicle glycoprotein 2A (SV2A) and shows diminished uptake in the frontal and anterior cingulate cortex in individuals with schizophrenia." (PMID 35507580, 2022). "Here, we investigated whether synaptic vesicle glycoprotein 2 A (SV2A) levels are related to glutamatergic markers and NAA in healthy volunteers (HV) and schizophrenia patients (SCZ)." (PMID 34282130, 2021). "In conclusion, SV2A levels are significantly lower in the FC and ACC in schizophrenia, and antipsychotic drug exposure at clinically relevant doses does not significantly alter SV2A levels or [3H]UCB-J-specific binding in the prefrontal and cingulate cortices of naïve rats." (PMID 31937764, 2020). "Therefore, we conducted a multimodal [11C]UCB-J PET and 1H-MRS imaging study to test the relationship between the proxy synaptic density marker SV2A and glutamate levels in vivo, hypothesising a negative relationship between the two in schizophrenia." (PMID 34282130, 2021). "Additionally, a study employing PET and 1H‐MRS found that SV2A levels were correlated with local Glu/Cr (glutamate relative to creatine) levels in healthy volunteers within the left hippocampus and anterior cingulate cortex, with diminished or absent correlations in patients with schizophrenia." (PMID 41437520, 2025).
Parkinson disease (16 papers, 2017 to 2026). A progressive degenerative disorder of the central nervous system characterized by loss of dopamine producing neurons in the substantia nigra and the presence of Lewy bodies in the substantia nigra and locus coeruleus. "With the exception of Parkinson’s disease, lower SV2A marker levels are generally associated with greater symptom severity, in particular cognitive dysfunction." (PMID 39134769, 2024). "To conclude, further research is required to determine whether the spatial and temporal pattern of SV2A changes could help to explain PD pathology, distinguish between PD-subtypes and/or atypical Parkinsonism, and could act as a therapeutic biomarker." (PMID 40672937, 2025). "The tracer [11C]UCB-J was further tested by visualization in vivo as a marker of synaptic SV2A density loss in rats with unilateral striatal lesions using 6-hydroxydopamine (6-OHDA) to model toxin-induced Parkinson’s disease or preformed α-synuclein fibrils to model progressive Parkinson’s disease." (PMID 35573314, 2022).